EPOR (erythropoietin receptor)
Description:
Receptor for erythropoietin, which mediates erythropoietin-induced erythroblast proliferation and differentiation. Upon EPO stimulation, EPOR dimerizes triggering the JAK2/STAT5 signaling cascade (By similarity). In some cell types, can also activate STAT1 and STAT3. May also activate the LYN tyrosine kinase (By similarity). [Isoform EPOR-T]: Acts as a dominant-negative receptor of EPOR-mediated signaling.
Synonyms: EPO-R
Tractability: Antibody: UniProt places it where antibodies can reach, with high confidence; its Gene Ontology location is reachable by antibodies, with high confidence; UniProt predicts a signal peptide or a membrane-spanning region; the Human Protein Atlas places it where antibodies can reach. PROTAC: UniProt records ubiquitination sites on it; a small molecule that binds it is known. Other modalities: an approved drug acts on it.
Target class: Membrane receptor
Gene: Protein-coding gene on chromosome 19 (11,377,207 to 11,384,343, reverse strand). Ensembl gene ENSG00000187266.
Subcellular location: Cell membrane; Secreted (Isoform EPOR-S)
Subcellular location (Human Protein Atlas): Plasma membrane; Nuclear speckles
Pathways (Reactome):
Signal Transduction: Erythropoietin activates Phosphoinositide-3-kinase (PI3K); Erythropoietin activates Phospholipase C gamma (PLCG); Erythropoietin activates RAS; Erythropoietin activates STAT5; Signaling by Erythropoietin
Gene Ontology:
Molecular function: erythropoietin receptor activity; identical protein binding; protein binding; cytokine receptor activity; transmembrane signaling receptor activity
Biological process: erythropoietin-mediated signaling pathway; signal transduction
Cellular component: extracellular region; plasma membrane; receptor complex; external side of plasma membrane; membrane
Genetic constraint (gnomAD): Loss-of-function variants: 22 observed, 39.9 expected, observed/expected ratio (o/e) 0.55, 90% interval 0.39 to 0.79. The upper end of that interval is the gene's LOEUF score, 0.79, which puts it in group 3 of 6, group 1 being the genes least tolerant of losing a copy. Missense variants: 601 observed, 676.59 expected, observed/expected ratio (o/e) 0.89, 90% interval 0.83 to 0.95. Synonymous variants: 312 observed, 299.49 expected, observed/expected ratio (o/e) 1.04, 90% interval 0.95 to 1.14.
Homologues: Orthologues: chimpanzee EPOR (99% identical), macaque EPOR (97% identical), pig EPOR (85% identical), dog EPOR (83% identical), mouse Epor (82% identical), rat Epor (81% identical), rabbit EPOR (80% identical), guinea pig EPOR (75% identical), tropical clawed frog epor (31% identical), zebrafish epor (28% identical), zebrafish il4r.1 (6% identical). Paralogues in human: CSF2RB (21% identical), MPL (20% identical), IL4R (16% identical), IL2RB (14% identical), IL9R (14% identical), IL21R (14% identical), IL7R (11% identical).
Diseases named in the same sentence as EPOR in open-access papers:
EPOR is named in the same sentence as 206 diseases in open-access papers, as found by Europe PMC text mining. Sharing a sentence is not in itself a finding about the gene and the disease. The quoted sentences say what the papers report.
anemia (80 papers, 2005 to 2026). A reduction in the number of red blood cells, the amount of hemoglobin, and/or the volume of packed red blood cells. "The related cytokines also decrease the expressions of erythropoietin receptor messenger ribonucleic acid contributing to the major cause of anemia." (PMID 40364122, 2025). "The EPOR (chr6: 216,150,503–216,156,409 bp) gene was discovered to be associated with the production of red blood cells, and severe anemia was observed in AD-infected mink few months after infection." (PMID 39071778, 2024). "Our work reveals novel EpoR functions, and suggests hypoxia, anemia, and other high-Epo syndromes as new diagnostic interpretations of increased red-cell size in the clinic." (PMID 34921133, 2021). "A mutation in erythropoietin (Epo) found in humans, which reduces its binding affinity for its receptor (EpoR), was shown to bias signaling output by EpoR and caused severe anemia in human patients." (PMID 31774398, 2019). "The restoration of EPOR specifically in erythroid lineages rescued the lethal phenotype, indicating that anemia is indeed the cause of in utero death." (PMID 24478716, 2014). "Targeted disruption of EPOR causes a marked reduction of primitive erythroblasts by E10.5–E11.5 and a profound anemia by E12.5." (PMID 24478716, 2014). "Mice deficient for EPO or EPO receptor (EPOR) genes die at embryonic day 13 (E13) because of severe anemia caused by deficiency in definitive erythropoiesis." (PMID 20142991, 2009). "Further studies are needed to assess whether anti-EPOR antibodies are on the causal pathway to adverse outcomes, including anemia, or are simply a marker of poor prognosis." (PMID 38344715, 2024). "Loss of EPO or EPOR causes death in utero due to severe anemia." (PMID 36895793, 2023). "Thus, the cardioprotective function of ESA is suggested to be caused, in part, by the direct action of EPO binding to EPOR in heart tissue along with improvement in anemia." (PMID 36140193, 2022). "Whether anti-EPOR antibodies are associated with the development or progression of ESA hyporesponsive anemia in patients on dialysis needs to be investigated by further longitudinal studies." (PMID 36140193, 2022). "A ≥2.5-fold increase in infiltration of CD163+EPOR+ TAMs was associated with malignant tumor phenotypes, such as the number of lung metastases, maximal diameter of lung metastases and pathologic grade as well as anemia." (PMID 32908942, 2020). "We further showed that the germline EpoR-deficient mice could be rescued from their embryonical lethal anemia by transgenic expression of EpoR under the control of the G1HRD promoter." (PMID 25790231, 2015). "In this study, we found that deletion of Mettl3 using the EpoR-Cre mouse led to microcytic/hypochromic anemia due to defective erythropoiesis along with impaired hemoglobin biosynthesis." (PMID 41805631, 2026). "While native EPO exerts both hematopoietic and tissue-protective effects via erythropoietin receptor (EPOR) homodimer activation, its clinical use beyond anemia is limited by adverse effects related to increased red blood cell production." (PMID 41596336, 2026). "These deleterious effects limit the patient populations that can benefit from EPO‐based ESAs, and therefore, an ESA that only activates the EPOR homodimer would be highly desirable as an alternative to pleiotropic EPO for the treatment of anemia." (PMID 40960423, 2025). "Efforts in these directions are underway, and we believe that an effective Ab‐based agonist of EPOR will soon be available as a therapeutic for anemia." (PMID 40960423, 2025). "The potential severity of these risks is exemplified by peginesatide, a pegylated dimeric peptide agonist of EPOR that gained clinical approval for the treatment of anemia." (PMID 40960423, 2025). "In other published literature, tyrosine phosphorylation of EPOR (EPOR-phosphotyrosine-343-Stat5 signaling axis) was essential for erythropoiesis in induced anemia." (PMID 38388899, 2024).
anemia (continued). "During mouse development and prior to death in utero due to severe anemia, mice that lack EPOR exhibit reduced neural progenitor cells, hypoxia sensitivity, and increased brain apoptosis." (PMID 38628440, 2024). "Continuous erythropoietin receptor activator (CERA) is a third‐generation erythropoiesis‐stimulating agent that was developed for the treatment of anemia." (PMID 34380180, 2022). "Recently, we detected autoantibodies to EPOR that can induce anemia by inhibiting EPO–EPOR interaction on erythroid progenitor cells." (PMID 36140193, 2022). "Our findings provide insight into the specific interaction between a phytoestrogen diarylheptanoid and Epo-EpoR in a hematopoietic system for the potential treatment of anemia." (PMID 35740448, 2022). "Even prior to severe anemia, embryonic EPOR−/− mice show reduced neuroepithelium and neural progenitor cells, increased brain apoptosis and neural cells with increased sensitivity to hypoxia." (PMID 34603036, 2021). "Those with anti-EPOR antibodies had significantly higher SLE disease activity and more severe anemia, suggesting that anti-EPOR antibodies have inhibitory function." (PMID 33796104, 2021). "Targeted deletion of EPO (EPO−/−) or EPOR (EPOR−/−) in mice results in embryonic death due to severe anemia." (PMID 34603036, 2021). "A transgene with EPOR expression restricted to erythroid tissue is able to rescue EPOR−/− mice from severe embryonic anemia and gives rise to viable ΔEPORE mice with EPOR restricted to erythroid tissue." (PMID 34603036, 2021). "Consistently, low levels of the EpoR regulator Gata1 result in embryonic anemia but normal adult erythropoiesis." (PMID 33566111, 2021). "Most EPO-related research in SLE has focused on the association between anemia and autoantibodies to EPO and EPOR." (PMID 33796104, 2021). "Other mechanisms of anemia induced by IL-6 include rapid hemodilution, impairment of erythroid proliferation, and maturation and downregulation of the membrane-bound erythropoietin receptor." (PMID 33535417, 2021). "Our study indicated that anemia in combination with a >2.5-fold increase in the percentage of CD163+EPOR+ TAMs had the worst prognosis." (PMID 32908942, 2020). "Because EPOR was expressed by TAMs and anemia can induce EPO secretion, which can activate the EPO-EPOR signal to promote the protumor functions of CD163+EPOR+ TAMs." (PMID 32908942, 2020). "EPO and EPOR on the surface of erythroid progenitor cells are required for red blood cell production and mice with targeted deletion of EPO or EPOR die during embryonic development of severe anemia." (PMID 32038269, 2019). "EPO is required for definitive erythropoiesis and knockout of EPO or EPOR in mice results in death in utero around day 13.5 due to disruption of erythropoiesis in the fetal liver resulting in severe anemia." (PMID 32038269, 2019). "Combined treatment of Siwu granules with EPO increased the expression of EPO and EPOR in the renal tissues and inhibited oxidative stress and inflammatory factors, improving the renal function and anemia." (PMID 31915448, 2019). "The restoration of EPO production as well as EPOR expression activates EPOR downstream signaling cascades, thereby resulting in the stimulation of erythropoiesis and correction of anemia." (PMID 30108502, 2018). "Observations of increased apoptosis in non-hematopoietic tissue in Epo or EpoR knock-out mice prior to the onset of anemia implied a functional role of Epo-EpoR signaling beyond erythropoiesis." (PMID 29393890, 2018). "EpoR-null embryos develop neurologic abnormalities prior to the development of lethal anemia, including decreased numbers of neural progenitor cells and hypoplasia of the forebrain and neural epithelium." (PMID 29084993, 2017). "We propose that the CID-dependent dimerization system combined with the EpoR intracellular domain and the Gata1 gene regulatory region generates a novel peroral strategy for the treatment of anemia." (PMID 25790231, 2015).
anemia (continued). "This regulated system of erythropoiesis worked as efficiently as the Epo-EpoR system in vivo and provided information regarding the possibility of a peroral strategy for anemia treatment combined with gene therapy." (PMID 25790231, 2015). "The embryonically lethal anemia observed in both JAK2- and STAT5-deficient mice, which resemble Epo- or EpoR-deficient mice, demonstrates the crucial roles of JAK2 and STAT5 in Epo-dependent erythropoiesis." (PMID 25790231, 2015). "In a multicenter, prospective, observational study of 279 kidney transplant recipients with anemia, the efficacy and safety of once-monthly continuous erythropoietin receptor activator (C.E.R.A)." (PMID 24883202, 2014). "Knockout of EPO (EPO−/−) or EPO receptor (EpoR−/−) in mice results in embryonic death due to severe anemia." (PMID 24918289, 2014). "As rhEPO is widely used in clinical practice for the treatment of anaemia associated with various disorders including cancer, the expression of EPO and EPOR in the kidney and especially in RCC has been a cause for concern." (PMID 23305401, 2013). "Possibly as a compensation to this, the erythropoietin receptor gene expression was significantly higher, while the down-stream signaling steps were repressed, perhaps contributing to the anemia of renal failure." (PMID 23809614, 2013). "In mice, deletion of EPO (Epo−/−) or EpoR (EpoR−/−) leads to angiogenic defects detectable at day E10.5, two days prior to the onset of severe anemia." (PMID 22567318, 2012). "When EPO levels increase (e.g., due to anemia or anti-anemia therapy), cell surface-resident EPOR's rapidly (and transiently) convert to activated EPOR-72K species." (PMID 22253704, 2012). "is the first continuous erythropoietin receptor activator developed for the control of anemia in patients with cancer." (PMID 17341293, 2007). "As the EpoR is redundant on the tumour cells, this verifies that the correction of anaemia is the explanation for the increased therapeutic outcome." (PMID 15999100, 2005). "Lewis lung carcinoma cells were examined for EpoR protein expression by Western blot analysis, using a murine anaemic spleen as a positive control, as anaemia stimulates the accumulation of EpoR-expressing erythroid progenitor cells in the spleen." (PMID 15999100, 2005). "We also examined whether the effects of canagliflozin on hemoglobin, hematocrit, and incident anemia were modified by anti-EPOR antibodies." (PMID 38344715, 2024). "The reduction in risk of anemia with canagliflozin was not modified by anti-EPOR antibodies at baseline (P for interaction = 0.27)." (PMID 38344715, 2024). "The production of RBCs in the bone marrow is controlled by erythropoietin (EPO), a hormone mainly produced and secreted by the kidneys in response to hypoxia and anemia, which binds to its receptor (EPOR) on the surface of erythroid progenitors in the bone marrow." (PMID 39666728, 2024). "Several studies reported that vitamin D supplementation could improve anemia by increasing erythropoietin production and erythropoietin receptor expression, reducing the secretion of proinflammatory mediators, and enhancing erythropoietin sensitivity." (PMID 35370939, 2022). "The implication that endogenous EPO may be sufficient to support tumor growth suggests that targeting EPOR on tumor cells is a relevant approach to attenuate tumor growth while enabling treatment with EPO to alleviate anemia." (PMID 36052260, 2022). "Two of the most advanced drugs developed by screening phage-displayed libraries of random peptides are the EpoR and TpoR peptide agonists that target the erythropoietin and thrombopoietin receptors for the treatment of anemia and idiopathic thrombocytopenic purpura respectively." (PMID 29485998, 2018). "Compared to blood loss, anemia in young CKD rats is associated with inappropriate responses in the HIF-EPO-EPO-R axis: kidney HIF2α and renal EPO are not increased, BM and bone EPOR levels, as well as bone pSTAT5 response to EPO are reduced." (PMID 29738538, 2018).
anemia (continued). "We herein present a case involving a 65-year-old Japanese woman with low-risk myelodysplastic syndrome whose erythropoiesis-stimulating agent treatment was switched from darbepoetin α to epoetin β pegol (continuous erythropoietin receptor activator) to treat transfusion-dependent anemia." (PMID 29047386, 2017). "A central concern, however, in the use of EPO to treat anaemia in cancer patients is whether tumour cells express EPOR and therefore could be stimulated to tumour growth." (PMID 27581518, 2016). "Administration of putative anti-angiogenic agents targeting Epo/EpoR may be limited by development of anemia due to the inhibition of erythropoiesis." (PMID 26919105, 2016). "EpoR-null mutant mice show a phenotype identical to Epo-null mice, which exhibit embryonic lethality at approximately embryonic day 13 (E13) due to severe anemia." (PMID 25790231, 2015). "EPO−/− and EpoR−/− mice die of severe anemia around embryonic day 13.5." (PMID 24918289, 2014). "The importance of EPO signaling through its cognate receptor was demonstrated by the identical phenotype of EPO-null and EPOR-null mice: fetal death at embryonic day 13.5 (E13.5) associated with severe anemia and the complete lack of definitive RBCs." (PMID 24478716, 2014). "Mice with targeted deletion of EpoR (EpoR−/−) exhibit increased apoptosis in the brain as early as day E10.5, thinning of the neuroepithelium, and smaller brain size prior to death around day E13.5 due to severe anemia." (PMID 22567318, 2012). "EPOR-/- fetuses exhibit increased apoptosis in the brain and a reduction in the number of neural progenitor cells, as well as increased sensitivity to hypoxia prior to significant anaemia or heart defects in the embryo proper." (PMID 20142991, 2009). "Erythropoietin receptor (EpoR) has been reported to be overexpressed in tumours and has raised safety concerns regarding the use of erythropoiesis-stimulating agents (ESAs) to treat anaemia in cancer patients." (PMID 18349818, 2008). "Indeed, the expression of EPOR has raised concerns about the safety of EPO treatment in cancer patients with anemia because EPO may stimulate cancer cell survival and tumor progression." (PMID 36052260, 2022). "In addition, although EpoR agonists drugs are initially aimed at treating anemia, it is starting to demonstrate the sign of pleiotropic effects for treating a wide range of complex disorders, including CVD, neurodegenerative disorders, spinal cord injury, and diabetic retinopathy." (PMID 32373157, 2020). "Moreover, XHSG could improve the erythrocyte immune functions and wound healing by enhancing the expression of EPOR and F2 in anemia." (PMID 29551975, 2018). "In the case of anemia in CKD patients, even when erythropoietin receptor activators are used at appropriate doses, 5–10% of CKD patients show insufficient clinical response." (PMID 39338353, 2024). "Anemia in chronic kidney disease (CKD) patients is treated with iron supplements and erythropoietin receptor activators." (PMID 39338353, 2024). "Taken together, our data clearly suggest that combined analyses of anemia and the percentage of CD163+EPOR+ TAMs were a better predictor for recurrence and survival in osteosarcoma lung metastasis patients than analyzing individual factors." (PMID 32908942, 2020). "Because EPO and EPOR are expressed in RCC (and in other cancers), the use of recombinant human EPO (rhEPO) to treat anaemia in cancer patients has been subject to considerable debate." (PMID 23305401, 2013). "Despite the frequent expression of EPO and EPOR in RCC, approximately 35% of RCC patients develop anaemia, whilst only 1-5% experience paraneoplastic polycythaemia." (PMID 23305401, 2013). "Clinicopathological correlations were performed for the frequency of Epo, EpoR and CD131 immunolabelling and jaundice, anaemia, acute renal failure, hypoglycaemia, pulmonary oedema and haemodynamic shock." (PMID 19930602, 2009).